TRPV5 (transient receptor potential cation channel subfamily V member 5)
Diseases named in the same sentence as TRPV5 in open-access papers (continued):
Sharing a sentence is not in itself a finding about the gene and the disease.
osteoporosis (4 papers, 2020 to 2025). A condition of reduced bone mass, with decreased cortical thickness and a decrease in the number and size of the trabeculae of cancellous bone (but normal chemical composition), resulting in increased fracture incidence. "In recent years, an increasing number of researchers have focused on investigating the association between TRPV5 function and various tissue layers in osteoporosis." (PMID 37198647, 2023). "As calcium and magnesium are key components of bone, we tested the hypothesis that Ghrelin-deficiency contributes to osteoporosis via reduced upregulation of the renal calcium channel TRPV5 and the heteromeric magnesium channel TRPM6/7." (PMID 38638279, 2024). "For instance, 1,25(OH)2D3, a conventional drug for osteoporosis treatment, can increase Ca2+ absorption but also inhibit TRPV5 expression in osteoclasts, leading to the inhibition of early osteoclast differentiation, activity, and bone loss." (PMID 37198647, 2023). "Several protein factors, directly or indirectly related to osteoporosis, exert their effects on TRPV5." (PMID 37198647, 2023). "Similarly, Alendronate, another TRPV5 inhibitor, has been shown to enhance bone mineral density and quality in patients with osteoporosis through the inhibition of TRPV5-mediated Ca2+ transmembrane transport." (PMID 40417213, 2025). "Investigations concerning the relationship between TRPV5 and osteoporosis (OP) primarily streams from its function in the absorption and translocation of Ca2+ icons, as well as its ubiquitous distribution throughout various tissues, including the bone, kidney, and placenta." (PMID 37198647, 2023). "In the future, the relationship between the osteoporosis microenvironment and TRPV5 will be more clearly elucidated, and drug development or disease diagnostic criteria centered on TRPV5 ion channels will provide more favorable conditions for the treatment of osteoporosis." (PMID 37198647, 2023). "Moreover, the development of TRPV5 agonists and inhibitors as anti-osteoporosis drugs is the ultimate goal of related research." (PMID 37198647, 2023). "This complicates the scenario in postmenopausal women since the reduction of estrogens with the concomitant increase in androgens leads to downregulation of TRPV5 channel expression contributing to osteoporosis by affecting bone homeostasis and Ca2+ reabsorption." (PMID 32471309, 2020).
Calcium nephrolithiasis (3 papers, 2015 to 2019). The presence of calcium-containing calculi (stones) in the kidneys. "Another research found a TRPV5 polymorphism (rs4236480) was associated with stone multiplicity of calcium nephrolithiasis, as the risk of stone multiplicity increased in patients carrying TT+CT genotype than those with CC genotype." (PMID 30666830, 2019). "In order to investigate the association between stone multiplicity and genotypes, we further examined whether the TRPV5 SNP rs4236480 genotypes were associated with the stone number of calcium nephrolithiasis patients." (PMID 26089600, 2015). "We found that a TRPV5 polymorphism (rs4236480) was observed to be associated with stone multiplicity of calcium nephrolithiasis, as the risk of stone multiplicity was higher in patients with the TT+CT genotype than in patients with the CC genotype (p = 0.0271)." (PMID 26089600, 2015). "The results may support a role of TRPV5 in the development of calcium nephrolithiasis in Taiwanese population." (PMID 26089600, 2015).
Hypercalcemia (3 papers, 2014 to 2025). An abnormally increased calcium concentration in the blood. "Global Klotho KO mice challenged with a diet low in Ca2+, PO34−, and vitamin D show hypercalcemia, renal Ca2+ wasting, osteopenia, and intestinal Ca2+ hyperabsorption, highlighting that the Ca2+ leak is likely a consequence of Klotho failing to anchor TRPV5 to the membrane." (PMID 40165603, 2025). "Whether the TRPV5 and TRPV6 overexpression in this context could directly contribute to tumourigenesis or represent a secondary event of hypercalcaemia needs to be further elucidated." (PMID 25164318, 2014).
hypocalcaemia (3 papers, 2013 to 2022). "The downregulation in renal TRPV5 expression promotes renal calcium wastage and hypocalcaemia in diabetics." (PMID 35898447, 2022).
Hypocalciuria (3 papers, 2018 to 2023). An abnormally decreased calcium concentration in the urine. "In addition, thiazide-induced hypocalciuria is also the result of increased calcium reabsorption in the distal tubule and upregulation of TRPV5, calbindins, and other related calcium transport proteins located in the distal tubule." (PMID 37510715, 2023). "Some researchers have suggested that the upregulation of TRPV5/6 and of ROMK1 and Maxi-K are involved in the pathogenesis of hypocalciuria and hypokalemia in NCC Ser707X knockin mice and human GS, respectively." (PMID 34046503, 2021).
adenoma (2 papers, 2014 to 2018). A neoplasm arising from the epithelium. "TRPV5 expression was also found to be increased in adenoma samples compared with that in normal parathyroid glands." (PMID 29659618, 2018). "In this work, the presence of TRPV5 and TRPV6 proteins and of their mRNAs was studied by using human parathyroid tissues, while their cellular localization and time expression were evaluated by immunocytochemical assay on primary human adenoma parathyroid cells." (PMID 25164318, 2014).
breast carcinoma (2 papers, 2017 to 2024). "The genes PRSS1, TRPV5 and PIP have so far been implicated in a few cancer types (pancreatic-, non-small cell lung- and breast cancer), while EphB6 and TRPV6 have been studied in relation to numerous cancer types." (PMID 29299148, 2017).
deafness (2 papers, 2010 to 2019). An inherited or acquired condition characterized by the complete loss of the ability to hear from one or both ears. "It is perhaps more than a coincidence, therefore, that the genes for TRPV5 and TRPV6 are located on chromosome 7q35 and 7q33-34 respectively in human and the locus of the non-syndromic deafness gene DFNB13 is located at the encompassing region on chromosome 7q34-36." (PMID 20113508, 2010).
diabetes (2 papers, 2022 to 2023). "Streptozotocin-induced diabetes significantly increases TRPV5 mRNA expression in rats, and renal immunofluorescence sections demonstrate a significant increase in TRPV5 expression." (PMID 37198647, 2023). "Studies have reported elevated urinary calcium levels along with decreased renal TRPV5 expression in diabetes." (PMID 35898447, 2022).
Hypertension (2 papers, 2018 to 2025). The presence of chronic increased pressure in the systemic arterial system. "Given calmodulin’s regulatory role in calcium handling within renal tubular cells—including modulation of TRPV5 channels and calcium reabsorption —its activation in the kidney may be linked to intrarenal calcium signaling disturbances driven by hypertension." (PMID 40426778, 2025).
non-small cell lung carcinoma (2 papers, 2018 to 2023). A group of at least three distinct histological types of lung cancer, including non-small cell squamous cell carcinoma, adenocarcinoma, and large cell carcinoma. "A reduced TRPV5 expression in tumor tissues is detected in non-small-cell lung cancer patients and associated with a shorter median survival time after surgical resection." (PMID 37892239, 2023). "The combined expression of TRPV5 and TRPV6 in tumor tissues exhibited promising prognostic value in non-small-cell lung cancer patients." (PMID 37892239, 2023).
Polyuria (2 papers, 2018 to 2021). An increased rate of urine production. "We previously showed in the full body GLUT9 KO mouse model that polyuria was accompanied by urine acidification evoking similar processes found in the hypercalciuric TRPV5 knock-out mice and thought to be mediated by the calcium sensing receptor." (PMID 30105595, 2018).
postmenopausal osteoporosis (2 papers, 2020 to 2023). Metabolic disorder associated with fractures of the femoral neck, vertebrae, and distal forearm. "TRPV5/6 agonists can prevent postmenopausal osteoporosis (PMOP) induced by estrogen deficiency in postmenopausal women and optimize bone calcium supply." (PMID 37198647, 2023). "Possibly, postmenopausal osteoporosis in women is produced by augmented levels of androgens, leading to downregulation of TRPV5 and increasing the loss of renal Ca2+ and bone mass." (PMID 32471309, 2020). "Thus, estrogen replacement therapy is an alternative that restores the expression and function of TRPV5 channels and alleviates postmenopausal osteoporosis." (PMID 32471309, 2020).
renal carcinoma (2 papers, 2019 to 2020). A carcinoma arising from the epithelium of the renal parenchyma or the renal pelvis. "(2018) showed that the expression of the calcium channel TRPV5 inversely correlates with the expression of the VDR in renal cancer cells." (PMID 32210800, 2020).
vitamin D deficiency (2 papers, 2018 to 2021). A nutritional condition produced by a deficiency of VITAMIN D in the diet, insufficient production of vitamin D in the skin, inadequate absorption of vitamin D from the diet, or abnormal conversion of vitamin D to its bioactive metabolites. "At mild vitamin D deficiency (500 IU/kg, 5 weeks), the increased expression levels of genes coding for TRPV5, calbindin D28K and NCX1 remained unaffected." (PMID 30038585, 2018).
Acidosis (1 paper, 2023). Abnormal acid accumulation or depletion of base. "Recent studies on the pH microenvironment of bone tissue and TRPV5 reveal that the occurrence of metabolic acidosis reduces the expression and function of TRPV5 and the absorption of Ca2+ at least at the mRNA level." (PMID 37198647, 2023).
asthma (1 paper, 2024). "The role of the other subfamilies of TPRV in VILI still needs to be elucidated and might be promising because they are reportedly involved in ovalbumin-induced asthma models (TRPV1, TRPV2, TRPV5), and lung epithelial injury caused by cigarette smoke, LPS, seawater inhalation and wood smoke (TRPV3)." (PMID 39664395, 2024).
basophilic leukemia (1 paper, 2015). "In addition, TRP currents including TRPV5 and TRPM7 are reduced by intracellular Mg2+ as well as other divalent such as Ba2+, Sr2+, Mn2+, and Zn2+ through charge shielding of PIP2 by cations in rat basophilic leukemia and T-lymphocyte and in heterologous expression systems." (PMID 26658739, 2015).
chronic kidney disease (1 paper, 2023). Impairment of the renal function secondary to chronic kidney damage persisting for three or more months. "This situation is analogous to increased expression levels of genes (TRPV5 and calbindinD-28K) responsible for Ca reabsorption in the proximal tubules of the kidney observed in mice with experimental chronic kidney disease." (PMID 37686643, 2023).
colon adenoma (1 paper, 2018). An adenoma that arises from the colon. "TRPV5 is poorly expressed or not expressed in normal colon tissues but is highly expressed in colon adenoma and adenocarcinoma." (PMID 29659618, 2018).
colorectal cancer (1 paper, 2018). A primary or metastatic malignant neoplasm that affects the colon or rectum. "It would be interesting to define the role of endothelial TRPV channels in angiogenesis and carcinogenesis as recent published data implies that TRPV3, TRPV4, TRPV5, TRPM4 and TRPC6 may be thought of as potential genes contributing to colorectal cancer tumorigenesis." (PMID 29914124, 2018).
diabetic kidney disease (1 paper, 2022). Progressive kidney disorder caused by vascular damage to the glomerular capillaries, in patients with diabetes mellitus. "Additionally, transient receptor potential vanilloid type 5 (TRPV5) is responsible for Ca2+ reabsorption in the distal tubuli, but expression declines during diabetic kidney disease." (PMID 36295832, 2022).
epilepsy (1 paper, 2025). A brain disorder characterized by episodes of abnormally increased neuronal discharge resulting in transient episodes of sensory or motor neurological dysfunction, or psychic dysfunction. "TRPV5 expression has been identified in diverse regions of the brain; however, it remains unknown how TRPV5 is implicated in the pathophysiological features of neurological diseases, including epilepsy." (PMID 40708193, 2025). "However, prior to this study, the involvement of TRPV5 in neuropathological conditions, particularly epilepsy, remained unknown." (PMID 40708193, 2025).
Gitelman syndrome (1 paper, 2025). Gitelman syndrome (GS), also referred to as familial hypokalemia-hypomagnesemia, is characterized by hypokalemic metabolic alkalosis in combination with significant hypomagnesemia and low urinary calcium excretion. "Studies in knock-in mouse models of Gitelman syndrome (with SLC12A3 mutations) suggest that increased expression of TRPV5 and TRPV6 channels in the DCT may also contribute." (PMID 40777730, 2025).
hearing loss (1 paper, 2025). "This highlights a gap in understanding: while TRPV5/TRPV6 are linked to calcium homeostasis and age-related hearing loss, their precise mechanistic roles (e.g., in sensory transduction vs. cellular calcium signaling) require further investigation." (PMID 40688696, 2025).
hydronephrosis (1 paper, 2024). Collection of urine in the renal pelvis that results in dilatation of the renal pelvis and calyces. "Trpv5 Atp6v1b1 dKO mice showed retarded growth directly after birth, 80% of these mice died within 6 weeks after birth and bilateral hydronephrosis in addition to abnormal dilation of the collecting ducts was observed." (PMID 38339056, 2024).
hyperparathyroidism (1 paper, 2024). Hyperfunction of the parathyroid glands resulting in the overproduction of parathyroid hormone. "This phenotypic picture is strikingly similar to the clinical phenotype observed in the individuals with homozygous TRPV5 mutations presented here (II-1, II-2, II-6), except for hyperparathyroidism in the proband." (PMID 38528055, 2024). "Hyperparathyroidism in the proband can be explained neither by GNAS nor TRPV5 mutations alone." (PMID 38528055, 2024).
hyperphosphatemia (1 paper, 2021). Abnormally high level of phosphate in the blood. "1,25(OH)2D/VDR–RXR acts in kidney to induce Klotho (a phosphaturic coreceptor for FGF23) to correct hyperphosphatemia, NPT2a/c to correct hypophosphatemia, and TRPV5 and CaBP28k to enhance calcium reabsorption." (PMID 33553988, 2021).
leukemia (1 paper, 2024). A malignant (clonal) hematologic disorder, involving hematopoietic stem cells and characterized by the presence of primitive or atypical myeloid or lymphoid cells in the bone marrow and the blood. "TRPV5 and TRPV6 are highly expressed in malignant states of human lymphocytes and leukemia Jurkat T cells, where they regulate cell proliferation." (PMID 39027429, 2024). "Other studies have shown that TRPV5 and TRPV6 are expressed in leukemia cell K562, and the increase in channels activates Ca2+/calmodulin-dependent kinase II (CaMKII), thereby increasing intracelluar Ca2+, regulating cell proliferation, differentiation, and resistance to apoptosis." (PMID 39027429, 2024).
nephrocalcinosis (1 paper, 2024). Nephrocalcinosis is a disorder that occurs when too much calcium is deposited in the kidneys. "The additional ablation of the B1 subunit of the H+-ATPase resulted in nephrocalcinosis, renal insufficiency, bone loss and poor growth in Trpv5 Atp6v1b1 dKO mouse model." (PMID 38339056, 2024). "There are differences between the Trpv5 KO model and our Cldn16 KO model in the context of nephrocalcinosis." (PMID 38339056, 2024). "The difference in phenotype between Trpv5 Atp6v1b1 dKO and Cldn16 Atp6v1b1 dKO extends beyond nephrocalcinosis." (PMID 38339056, 2024). "Thus, urine acidification was shown to be an important factor preventing the formation of calcium precipitants and thus, nephrocalcinosis in Trpv5 KOs." (PMID 38339056, 2024). "The injury caused by nephrocalcinosis cannot explain the complex phenotype of Trpv5 Atp6v1b1 dKOs, especially since other mouse models with nephrocalcinosis (Cldn2 KO and Cldn10 ksp cKO) do not develop this severe pathology." (PMID 38339056, 2024). "In contrast to Trpv5 Atp6v1b1 dKO, in our Cldn16 Atp6v1b1 dKO the alkalinization in the urine did not lead to nephrocalcinosis." (PMID 38339056, 2024). "Urine alkalinization, caused by the deletion of Atp6v1b1, was shown to be important in inducing nephrocalcinosis in hypercalciuric mice lacking transient receptor potential vanilloid 5 (TRPV5)." (PMID 38339056, 2024).
pancreatic cancer (1 paper, 2014). "Our finding predicts that, the TRP (Ca2+) channel-related genes (TRPV5 and TRPM6) and KCNK (K+) channel-related genes in the ion transport pathway are possible biomarkers of pancreatic cancer survival." (PMID 24565114, 2014).
parathyroid adenomas (1 paper, 2014). "The comparative quantitative PCR showed that parathyroid adenomas had a lower level of expression with respect to the pool of normal parathyroid glands (P < 0.001), both for TRPV5 and TRPV6 genes, which was on average 16 and fourfold less respectively." (PMID 25164318, 2014). "Our findings probably suggest that altered TRPV5 and TRPV6 expression might be associated with parathyroid adenoma." (PMID 25164318, 2014). "In the present study, for the first time, we provide evidence of the presence of TRPV5 and TRPV6 in human parathyroid glands and their protein overexpression in the parathyroid adenomas." (PMID 25164318, 2014). "All in all, our results show the presence of TRPV5 and TRPV6 channels in both normal parathyroid glands and parathyroid adenomas." (PMID 25164318, 2014). "Semi-quantitative and quantitative PCR was carried out to evaluate the presence of TRPV5 and TRPV6 mRNAs in sporadic parathyroid adenomas and normal parathyroid glands." (PMID 25164318, 2014). "Taking into account the regulatory role of the BSPRY and the involvement in cell proliferation of TRPV5/TRPV6, we investigated the presence of both channels in parathyroid adenoma and in parathyroid normal gland, either at mRNA or protein level." (PMID 25164318, 2014).
Seizure (1 paper, 2025). A seizure is an intermittent abnormality of nervous system physiology characterized by a transient occurrence of signs and/or symptoms due to abnormal excessive or synchronous neuronal activity in the brain. "Given the involvement of TRPV channels in reactive gliosis and neuroinflammatory processes following epileptic seizures, we hypothesized that TRPV5 might also be associated with glial activation and neuroinflammatory responses following epileptic injury." (PMID 40708193, 2025). "In the present study, econazole effectively reduced TRPV5 expression in activated microglia following epileptic seizure and LPS stimulation, and further induced the disruption of AKT/NF‐κB activation, NLRP3 inflammasome complex assembly, and the production of proinflammatory cytokine IL‐18." (PMID 40708193, 2025).
status epilepticus (1 paper, 2025). Status epilepticus is defined as a continuous seizure lasting more than 30 min, or two or more seizures without full recovery of consciousness between any of them. "Herein, we show that TRPV5 expression is upregulated in the hippocampus of a pilocarpine‐induced status epilepticus (PCSE) model, predominantly in activated microglia." (PMID 40708193, 2025).
vestibular disorder (1 paper, 2025). Pathological processes of the vestibular labyrinth which contains part of the balancing apparatus. "Additionally, Klotho downregulation decreases transient receptor potential vanilloid 5(TRPV5) and TRPV6 levels, altering inner ear Ca2+ regulation and causing sensory cell transduction defects that manifest as auditory or vestibular disorders." (PMID 40737282, 2025).